NEIL3 (nei like DNA glycosylase 3)
Diseases named in the same sentence as NEIL3 in open-access papers (continued):
Sharing a sentence is not in itself a finding about the gene and the disease.
cancer (continued). "Next, we discovered that NEIL3 expression was strongly positively correlated with DNA methyltransferase gene expression in most cancers." (PMID 36612106, 2022). "This enzyme is co-distributed with BRG1 at highly acetylated promoters of genes such as CDK4, LIG1, or NEIL3, which are responsible for cancer cell growth and the removal of DNA damage." (PMID 31614656, 2019). "The upregulation of NEIL3 appears to be involved in the maintenance of cancer cell growth or the progression of malignancy." (PMID 30591675, 2018). "Further, our data shows that the loss of NEIL3 leads to decreased replication fork speed and increased replication-associated DSBs, which exhaust RPA levels in cancer cells and compromised HR dependent repair." (PMID 29348879, 2017). "The APOBEC3B expression level was significantly higher in the group of cancers with a high NEIL3 expression level than in the group of cancers with a low NEIL3 expression level in 10 of the 13 (76.9%) cancer types." (PMID 27042257, 2016). "Then, the median mutation loads for each cancer type and the median NEIL1, NEIL2, and NEIL3 expression values normalized to the expression value of the constitutive housekeeping gene YWHAZ (ENSG00000164924) were analyzed to identify correlations." (PMID 27042257, 2016). "In this study, the 0.5-fold, 0.5-fold, and 2.5-fold values of the median expression value in noncancerous tissue samples of each organ were used as cut-off values to dichotomize the NEIL1, NEIL2, and NEIL3 expression values in the cancer cases, respectively." (PMID 27042257, 2016). "In conclusion, our study indicates that the abnormal expressions of NEIL1, NEIL2, and NEIL3 are likely to be involved in mutagenesis in human cancer." (PMID 27042257, 2016). "A subset of the cancer types exhibited reduced NEIL1 and NEIL2 expressions and elevated NEIL3 expression, and such abnormal expressions of NEIL1, NEIL2, and NEIL3 were also significantly associated with the mutation loads in cancer." (PMID 27042257, 2016). "On the other hand, the level of NEIL3 mRNA expression was significantly increased in tumor tissue, compared with normal tissue, in all 13 cancer types (100%)." (PMID 27042257, 2016). "Results revealed that although we observed high variation within the different cancer samples from the same tissue, tumor samples in general displayed a higher expression of NEIL3 than the corresponding normal tissues, except for testis and pancreas." (PMID 19426544, 2009). "Furthermore, Gene Set Cancer Analysis (GSCA) was applied to study the impact of NEIL3 methylation on outcomes of KIRC." (PMID 36816967, 2023). "More importantly, patients with a higher expression of NEIL3 were revealed to be more sensitive to chemotherapeutic regimens and immune checkpoint inhibitors in selected cancers, implying that NEIL3 may be an indicator for therapeutic administration." (PMID 36612106, 2022). "Hence, in this study, we performed a genome-wide, multiomics analysis to assess the pan-cancer characteristics of NEIL3, including expression differences, prognostic value, genetic mutations, related pathways, and immunological features." (PMID 36612106, 2022). "Previous studies demonstrated the oncogenic role of NEIL3 in several cancers." (PMID 36612106, 2022). "Notably, we discovered that NEIL3 expression was upregulated in COAD cancer cells at the protein level, but reduced at the mRNA level." (PMID 36612106, 2022). "Therefore, NEIL3 overexpression levels exert different prognostic effects in different cancers, and further comprehensive evaluation of the magnitude of NEIL3 value as an independent prognostic biomarker in cancer is still needed." (PMID 36497204, 2022). "This study suggests that high NEIL3 levels exert different prognostic effects in different cancers." (PMID 36497204, 2022). "High NEIL3 expression may promote cancer phenotype by increasing genomic instability and/or interfering with other DNA repair." (PMID 35308531, 2022).
cancer (continued). "NEIL3 exhibited a wide range of genomic alterations among various types of cancers." (PMID 36612106, 2022). "We have focused on NEIL3 and circNEIL3 in cancer development, progression and prognosis." (PMID 36497204, 2022). "Elevated NEIL3 expression was significantly correlated with lower DSS in 13 cancers." (PMID 36612106, 2022). "Additionally, evaluation of the association between NEIL3 and MMR genes further confirmed its oncogenic role as a DNA damage repair enzyme in cancers." (PMID 36612106, 2022). "Notably, we characterized the relationship between NEIL3 expression and chemotherapy drug resistance, as well as immunotherapy sensitivity, across cancers." (PMID 36612106, 2022). "NEIL3 expression appears to be increased in the C1, C2, and C4 subtypes of most cancers." (PMID 36612106, 2022). "This section will focus on the latest frontiers of NEIL3 in cancer." (PMID 36497204, 2022). "NEIL3 promotes the proliferation of cardiac fibroblasts and neural progenitor cells in the brain and tends to be overexpressed in cells with a high proliferative capacity, such as cancer cells and those in the bone marrow." (PMID 33879165, 2021). "In this study, we addressed whether NEIL3 is required to overcome oxidative and replication-associated DNA damage and examined the therapeutic advantage of aberrant NEIL3 in cancer cells." (PMID 29348879, 2017). "In addition, the total mutation loads were significantly higher in the group of cancers with the higher NEIL3 expression levels in 7 of the 13 (53.8%) cancer types." (PMID 27042257, 2016). "Next, we attempted to investigate the expression statuses of NEIL1, NEIL2, and NEIL3 in each cancer type and to determine whether their abnormal expressions were associated with the mutation load of each cancer." (PMID 27042257, 2016). "Interestingly, we found increased NEIL3 expression in 16 of 18 cancer tissues compared to normal tissues." (PMID 19426544, 2009). "The expression of NEIL3 in multiple human cancers was also examined." (PMID 19426544, 2009). "NEIL3 is a member of the DNA glycosylase family whose expression is tightly regulated in time and space, with high expression mainly in cells with high proliferative capacities such as embryos, thymus, spleen, bone marrow and cancer, and plays a vital role in recognizing and cleaving damaged bases." (PMID 36497204, 2022). "Therefore, we evaluated whether the cancer-promoting effects of NEIL3 in NSCLC are mediated by PI3K/AKT/mTOR signaling." (PMID 35535347, 2022). "In addition, NEIL3 shows a role in predicting the progression, treatment responsiveness and survival of cancer patients, and it may be an independent prognostic indicator for certain cancers." (PMID 36497204, 2022). "Thus, we investigated the correlation of NEIL3 expression and neoantigen levels across cancers." (PMID 36612106, 2022). "However, little is known regarding the immunological features of NEIL3 among cancers." (PMID 36612106, 2022). "However, some mechanistic aspects have not fully been clarified yet, e.g., NEIL1, NEIL2 and NEIL3 triple-knockout mice were not prone to cancer and do not have increased mutational frequency produced by defective BER." (PMID 32252452, 2020). "Using data for 13 cancer types from the TCGA database, we revealed that the median somatic total and SNP-type mutation loads exhibited significant inverse correlations with the median NEIL1 and NEIL2 expression levels and a significant positive correlation with the median NEIL3 expression level." (PMID 27042257, 2016). "Our demonstration of a correlation between NEIL3 expression and APOBEC3B expression may explain why an increase in NEIL3 expression is associated with the somatic mutation load, since APOBEC3B is involved in mutagenesis in multiple distinct human cancers." (PMID 27042257, 2016).
cancer (continued). "Based on the results of immunocytes infiltration, TMB, and immune subtypes, we preliminarily presented the potential impact of NEIL3 expression on TME and the phenotypic changes in selected cancers." (PMID 36612106, 2022). "PPI analysis showed potential interactions between three cancer driver genes (AKT1, KRAS, and PIK3CA) and candidate genes (CCNE2, RAD51, and NEIL3)." (PMID 36233194, 2022). "circ-NEIL3 (human chromosome 4 [chr4]:178274462-178,281,831) overexpression in PDAC facilitates cancer proliferation and metastasis through circ-NEIL3/miR-432-5p/adenosine deaminases acting on the RNA 1 (ADAR1) axis." (PMID 36452037, 2022). "NEIL3 initiates base excision repair to maintain genomic stability, and NCAPG2 is involved in mitosis, DNA repair, and histone regulation and has a vital role in inhibiting cancer cell proliferation." (PMID 37509173, 2023). "DNA methylation can serve as a biomarker for the prognosis of common cancers, supporting our finding that KIRC patients with hypomethylated NEIL3 may have worse survival outcomes." (PMID 36816967, 2023). "Our study revealed that different NEIL3 expression levels and non-silent mutation rates influence the ICI response to some extent, which relies on cancer and ICI types." (PMID 36612106, 2022). "In our analysis, NEIL3 expression was positively correlated with pro-tumour chemokine receptors, such as CCR1, to some extent, but negatively correlated with anti-tumour receptors, such as CX3CR1, across cancers." (PMID 36612106, 2022). "Metastasis is the prominent feature of advanced cancers, and NEIL3 was correlated with many metastasis-inducing chemokines, such as CXCL10, which confirms our previous result that NEIL3 is related to an advanced stage and poorer prognosis in cancers." (PMID 36612106, 2022). "Firstly, we evaluated the mRNA expression of six DDR-related genes in NSCLC tissues in GEPIA, which demonstrated that CDC25C, NEIL3, H2AFX, NBN, XRCC5 and RAD1 were all significantly higher expressed in NSCLC cancer tissues compared to with normal lung tissues." (PMID 36408135, 2022). "Moreover, a significant positive correlation was found between the NEIL3 and APOBEC3B expression levels in 10 (76.9%) cancer types." (PMID 27042257, 2016). "The effects of abnormalities in the DNA glycosylases NEIL1, NEIL2, and NEIL3 on human cancer have not been fully elucidated." (PMID 27042257, 2016). "However, NEIL3 expression is observed in thymus and testis tissues and some cancers, and HEK293T cells are not a member of either category." (PMID 41359387, 2025). "In total, 27 cancers presented NEIL3 alterations, whereas only 5 cancers showed no alterations." (PMID 36612106, 2022). "Notably, higher expression of NEIL3 is positively correlated with higher EMT activity in BLCA, LIHC, and THCA, which implied the potential reason for the poorer prognosis and metastasis of these three kinds of cancers to some extent." (PMID 36612106, 2022). "Notably, there were negative correlations between NEIL3 expression and the C3 immune subtype in most types of cancers." (PMID 36612106, 2022). "However, research on NEIL3 and circNEIL3 with cancers is still lacking, especially the number of studies related to the mechanism, prognosis and treatment is scarce and needs further exploration." (PMID 36497204, 2022). "GSEA showed that the pathway of PI3K/AKT/mTOR, G2/M checkpoints, and E2F target were abnormally activated in NEIL3 patients while western blot revealed that NEIL3 could partially activate the PI3K/AKT/mTOR signaling pathway, which might be responsible for the cancer-promoting effects of NEIL3." (PMID 35535347, 2022). "Herein, by conducting a pan-cancer analysis, this study has examined the immunological and oncogenic role of NEIL3 in TME across cancers for the first time, which may provide insight into the potential of NEIL3 in clinical strategies." (PMID 36612106, 2022).
cancer (continued). "In our study, NEIL3 is positively correlated with six types of immune cell infiltration, including B cells, CD4 T cells, CD8 T cells, neutrophils, macrophages, DCs in KIPAN, KIRC, and LIHC, indicating that these three types of cancers may be inflamed tumors." (PMID 36612106, 2022).
tumor (25 papers, 2009 to 2025). "HNRNPA2B1 also plays a role where circular RNA from the NEIL3 gene (known as circNEIL3) is packed into exosomes and transferred to tumor-associated macrophages within the tumor microenvironment." (PMID 38474421, 2024). "Increased NEIL3 expression was related to advanced stage and larger tumor size as an independent diagnostic factor of poor prognosis in LUAD patients." (PMID 33879165, 2021). "Regarding the mutator phenotype, we identified BRCA2 and NEIL3 to be associated with higher mutational burden (i.e., 20 mutations/tumor) in tumors in Caucasians." (PMID 32300177, 2020). "In glioma, the circular RNA of exon-encoded origin by Nei Like DNA Glycosylase 3 (circNEIL3) is packaged into exosomes by hnRNPA2B1 and transmitted to infiltrated tumor-associated macrophages, conferring the immunosuppressive ability, which will support and promote tumor progression." (PMID 40699709, 2025). "As for the potential mechanism of NEIL3 in the onset and progression of the tumor, previous studies have indicated that it may be associated with the dysfunction of telomere." (PMID 34659404, 2021). "However, it is critical to examine the genetic status of a given tumor for NEIL3 deletion, amplification or mutation to determine a better treatment outcome." (PMID 29348879, 2017). "Our findings show that NEIL3 downregulation significantly reduces tumor volume and weight, suggesting a pro-tumorigenic function in EC." (PMID 39910812, 2025). "Our findings support this, demonstrating that NEIL3 overexpression increases β-catenin and cyclin D1 levels, potentially promoting cell proliferation and tumor growth." (PMID 39910812, 2025). "We further verified the relation between the expression of tumor-infiltrating lymphocytes (TILs) and NEIL3 via the TISIDB database." (PMID 36816967, 2023). "Studies have identified the potential of NEIL3 to modulate the immune microenvironment and promote tumor progression." (PMID 36816967, 2023). "Our results showed that NQO1 was correlated with the expression of the DNA repair gene NEIL3 (Pearson correlation coefficient), suggesting its role as a tumor control gene." (PMID 35308531, 2022). "Generally, NEIL3 is positively correlated with DNA MMR genes and methyltransferase expression in a majority of tumors, and the association between NEIL3 expression and EMT pathway activity is tumor-specific." (PMID 36612106, 2022). "Regarding prognosis, high NEIL3 levels were positively associated with advanced TNM stage, tumor volume, tumor resistance and low survival time." (PMID 36497204, 2022). "The analysis revealed that NEIL3 expression was generally low in normal tissues, except bone marrow, and upregulated in all 21 types of tumor cell lines." (PMID 36612106, 2022). "Combined with the neoantigen, tumor mutational burden (TMB), and microsatellite instability (MSI) results, a strong relationship between NEIL3 and the TME was observed." (PMID 36612106, 2022). "TIMER data showed that NEIL3 expression increased in 19 kinds of tumor tissues compared to adjacent normal tissues, especially in LUAD." (PMID 33879165, 2021). "In the present study, we revealed that NEIL3 expression is significantly upregulated in tumor tissues and HCC cell lines." (PMID 34659404, 2021). "TIMER and ImmuCellAI analyzed relationship between NEIL3 expression and the abundance of tumor-infiltrating immune cells in LUAD." (PMID 33879165, 2021). "The mRNA expression of NEIL3 was significantly higher in tumor tissues than that in the corresponding adjacent tissues (fold change = 9.73; P = 0.002)." (PMID 34659404, 2021). "We further established two nomograms for OS and DFS, respectively, based on tumor NEIL3 level and other independent prognostic factors, which were identified via multivariate analyses." (PMID 34659404, 2021).